FGFR2 (fibroblast growth factor receptor 2)
Diseases named in the same sentence as FGFR2 in open-access papers (continued):
Sharing a sentence is not in itself a finding about the gene and the disease.
breast carcinoma (continued). "Subsequent direct sequencing of the products verified that predominantly the transcript of FGFR2-IIIb is present in tumor tissue of sporadic breast cancer patients." (PMID 23527311, 2013). "In a small group of ErbB2-positive breast cancer patients treated with lapatinib, those whose tumors had elevated levels of FGFR2 had a shorter time to progression than the low FGFR2 group." (PMID 23343422, 2013). "Studies from genomewide association studies (GWASs) in breast cancer reveal SNPs in five genes (TNRC9, FGFR2, MAP3K1, H19, and LSP1) are associated with breast cancer susceptibility in European population." (PMID 22778704, 2012). "In conclusion, our results demonstrate that FGFR1 is crucial for S115 breast cancer cell proliferation and tumor growth and angiogenesis, whereas FGFR2 and FGFR3 are less critical for the growth of these cells." (PMID 23185502, 2012). "FGFR2 exon switching from the IIIb to the IIIc isoform has been observed during epithelial cell tumor progression, notably in breast cancer." (PMID 22007291, 2012). "Nuclear localisation of FGFR2 suggests an important additional role for this protein in breast development and breast cancer, in addition to its function as a classical cell surface receptor." (PMID 21418638, 2011). "Simultaneous consideration of overall association and intervention interaction point to genomic regions in the vicinity of FGFR2 and MRPS30 genes as relevant to breast cancer risk among postmenopausal women." (PMID 21702935, 2011). "SNPs rs2981582 and rs2981578, located in a linkage disequilibrium block (LD block) within intron 2 of the fibroblast growth factor receptor 2 gene (FGFR2), are associated with a mildly increased breast cancer risk." (PMID 21767389, 2011). "mRNA levels of FGFR2 and three fibroblast growth factor genes (FGFs) were measured in primary fibroblast and epithelial cell cultures from 98 breast cancer patients and correlated to their rs2981578 genotype." (PMID 21767389, 2011). "If overexpression of FGFR2 in breast cancer was related to genotype, it is doubtful whether overexpression of FGFR2 in 12% of tumours, even if only possible on a high risk allele background, would in itself, account for the increase in clinical risk in breast cancer." (PMID 21418638, 2011). "Nuclear staining for FGFR2 and its importance in human breast cancer has been highlighted by this study." (PMID 21418638, 2011). "In contrast, interactions with several subject characteristics have been identified for E-alone, including family history of breast cancer, benign breast disease, and again FGFR2 SNP rs3750817." (PMID 21702935, 2011). "The most significant association was observed for FGFR2 rs2981582, a variant previously shown to be associated with increased risk of BRCA2-related breast cancer." (PMID 21060860, 2010). "Previously identified breast cancer susceptibility loci had the most significant associations among BRCA2 mutation carriers (FGFR2: per allele and TOX3: per allele )." (PMID 21060860, 2010). "Common genetic variation in loci encoding for FGFR2 and MAP3K1 influences risk of breast cancer, and these genes were previously found to be somatically mutated in diverse neoplasias including breast cancer." (PMID 21124932, 2010). "Two additional genome wide association studies also recently identified SNPs in FGFR2 and TNRC9 as breast cancer susceptibility loci." (PMID 18437204, 2008). "In addition, as FGFR2 has been shown to be overexpressed or amplified only in a small percentage of breast cancers, it is possible that the association with breast cancer risk could be stronger and more clinically relevant for the small subset of tumors that express high levels of the receptor." (PMID 18437204, 2008). "The level of FGFR-2-IIIb present on breast cancer cell lines was sufficient for KGF stimulation of breast cancer cell proliferation." (PMID 9184170, 1997). "These discrepancies highlight the complexity of FGFR2’s role in breast cancer." (PMID 40748883, 2025).
breast carcinoma (continued). "Hence, genetic variations within the FGFR2 gene have pinpointed it as a potential contributor to the onset of breast cancer." (PMID 40748883, 2025). "However, the functional role of FGFR2 in breast cancer, particularly in triple-negative subtypes, remains poorly understood." (PMID 41318657, 2025). "There are some genetic association studies conducted on Bangladeshi Breast cancer and cervical cancer population to evaluate susceptible single nucleotide polymorphisms of INSIG2, HLA-DRB1, GCNT1P5, IL1β, IL4R, IL6, FGFR2, CYP1A1, ESR1 genes and disease outcome." (PMID 40920780, 2025). "Several studies have done the mRNA or protein expression of FGFR2 in breast cancer." (PMID 40748883, 2025). "FGFR2 might be a promising therapeutic target not only for cholangiocarcinoma with fusion but also for esophagus/stomach cancer and breast cancer with FGFR2 alterations." (PMID 41226813, 2025). "One potential explanation for the link between the FGFR2 rs2981578 AA genotype and breast cancer, both in our investigation and in studies conducted on different populations, might be attributed to differences in FGFR2 expression." (PMID 40748883, 2025). "On the other hand, FGFR2-4 amplifications represent approximately 1–2% of all breast cancer cases." (PMID 38255923, 2024). "About 3.6% of triple negative breast cancers carry FGFR2 amplification and it is hypothesized to regulate breast cancer development by promoting self-renewal through the NF-kB pathway." (PMID 39796710, 2024). "HER2+ breast cancer cells that are lapatinib-resistant have been found to overexpress FGFR2 levels." (PMID 39596875, 2024). "In one study that was directed towards FGFR2, it was noted that because of the single nucleotide changes in the sequence of Intron 2 at two positions, the reported altered binding of transcription factors lead to increase expression of FGFR2 in breast cancer." (PMID 39668814, 2024). "Moreover, they found that an increased Fgfr2 resulted in a lower Brca1, promoting tumorigenesis in basal-like mammary tumours." (PMID 39596875, 2024). "In previous studies, FGFR2 has mainly been related to breast cancer." (PMID 37895309, 2023). "The transcript isoform switch of FGFR2 detected by TEQUILA-seq across breast cancer subtypes is a hallmark of epithelial-to-mesenchymal transition associated with the invasiveness and aggressiveness of breast cancer cells." (PMID 37553321, 2023). "FGFR2 is considered to be a susceptibility gene for breast cancer, FGFR4 is a driving factor for breast cancer, and FGFR1 overexpression is found in nearly 50% of breast cancer patients." (PMID 37490511, 2023). "However, interestingly, we found that several non–breast cancer tissues had higher frequencies of FGFR2 Y375C expression than breast cancer tissues did." (PMID 37980453, 2023). "Besides this, ID4, SEMA3F, FOXD, KCNK5, WNK4 and ECM1 associate with chemoresistance origin and SOX5, ITM2A, SNCG, EPHA4, NTS, FGFR2 and ENPEP associate moreover with breast cancer tumorigenesis." (PMID 37239828, 2023). "While KRAS and FGFR2 alterations are infrequent in breast cancer, these alterations may be extremely significant in the prognosis and treatment of their disease." (PMID 37805590, 2023). "For example, three SNPs, rs2981578, rs45631563 and rs35054928, of fibroblast growth factor receptor 2 (FGFR2) are mapped to transcriptional silencer elements and enhance silencer activity, resulting in lower FGFR2 expression and increased risk of breast cancer." (PMID 37533175, 2023). "Breast cancers with a longer mean transit time in the time-intensity curve on CEUS were 10 times more likely to be associated with the SNPs-rs2275237 in ARNT and rs755793 in FGFR2 compared with those with a shorter mean transit time." (PMID 37120792, 2023).
breast carcinoma (continued). "FGFR2 alterations in breast cancer may represent infrequent but highly promising targets for futibatinib." (PMID 37980453, 2023). "Likewise, FGFR2 activation maintained mammary tumor-initiating populations in MMTV-PyMT mice, an aggressive model of luminal breast cancer." (PMID 37800138, 2023). "Amplification (predominantly observed in triple-negative breast cancer, 4%) and mutation (e.g., K660N) of FGFR2 occur frequently in breast cancer." (PMID 35494629, 2022). "First, activated FGFR2 could significantly inhibit the activity of ER modulators and reduce the sensitivity of breast cancer patients to anti-estrogen therapy." (PMID 35668376, 2022). "Indeed, FGFR2 inhibitors added to HER2-positive breast cancer cells after failure of treatment with the anti-HER2 drug lapatinib suggest a switch in cell addition to signalling inhibitors." (PMID 35193394, 2022). "cfDNA has potential for analysis of FGFR2 amplification in gastric and breast cancers." (PMID 35402233, 2022). "Therefore, future studies on the mechanism of HON targeting FGFR2 and Notch signaling in overcoming breast cancer resistance to TAM are needed." (PMID 36601474, 2022). "Furthermore, high-level FGFR2 amplification has been suggested to be associated with poor prognosis in several types of cancer, including GC, CRC, and breast cancer." (PMID 35342406, 2022). "Combination therapies might therefore elevate the response rates in FGFR2amp tumours, as proposed for FGFRi–CDK4/6i combination therapy in patients with breast cancer with FGFR2 and CCND1 amplifications." (PMID 35948633, 2022). "In the case of FGFRs, the presence of activating gene mutations in the FGFR axis, of various forms, has been reported in up to 18% of breast cancers, including FGFR1 and FGFR2 amplifications, point mutations in the ligand-binding region and oncogenic fusion proteins." (PMID 35193394, 2022). "Additionally, FGF7/FGFR2 signaling was found to abolish the anti-estrogenic effect of progesterone in breast cancer cells." (PMID 36009407, 2022). "In conclusion, FGF7 and FGF10 in the breast cancer microenvironment might regulate FGFR2 signalling-dependent breast cancer cell behaviour through complementary molecular mechanisms." (PMID 35193394, 2022). "Additionally, the FGF7/FGFR2 axis has been identified as driving tamoxifen resistance in breast cancer cells (T47-D, MCF-7)." (PMID 34830951, 2021). "Indeed, Western blotting with an antibody raised against the N-terminal region of FGFR2 detected a band at approximately 200 kDa, a lower mobility than endogenous FGFR2 in FGFR2-amplified MFM-223 breast cancer cells and the PDX HCI-016 (140–150 kDa)." (PMID 34344433, 2021). "Various FGFR2 alterations are detected in breast cancer, yet it remains unclear if activation of FGFR2 signaling initiates tumor formation." (PMID 34514747, 2021). "Moreover, in human breast cancer tissues, FGF stimulation causes nuclear translocation of FGFR2, which interacts with the transcriptional factor STAT5 and increases expression of STAT5 target genes and proteins." (PMID 33924850, 2021). "Activating FGFR2 missense mutations or amplifications can occur in cancers of the stomach, breast, lung, endometrium, and ovary, and overexpression of the FGFR2b-specific ligand FGF10 is linked to worse prognosis in breast cancer." (PMID 34007277, 2021). "FGF/FGFR2 signaling axis plays an important role in the development of breast cancer." (PMID 32432040, 2020).
breast carcinoma (continued). "To showcase our method, we evaluate associations between breast cancer susceptibility and SNPs in estrogen receptor alpha (ESR1), fibroblast growth factor receptor 2 (FGFR2), RAD51 homolog B (RAD51B), and TOX high mobility group box family member 3 (TOX3) genes, without access to raw genotype data." (PMID 32287273, 2020). "Our findings suggest that known candidate genes like FGFR2, ESR1, VDR, or BRCA2 could be associated with breast cancer in Uruguay and other admixed Latin American populations." (PMID 33126731, 2020). "Supporting this possibility that FGFR2 signaling could be maintaining the self-renewal and differentiation capabilities of breast cancer stem cells (BCSCs), FGFR2 overexpressing cells are resistant and proliferate under lapatinib selection." (PMID 32676501, 2020). "Some studies have shown that long non-coding RNA NONHSAT101069, SIRT6 protein, transforming growth factor (TGF-β), fibroblast growth factor receptor (FGFR) 4 rs1966265 and FGFR2 rs2981578 get involved in anthracycline resistance in breast cancer, as well as other factors." (PMID 33102228, 2020). "FGFR2-amplified breast cancer was found with frequencies of up to 4.4%." (PMID 32852708, 2020). "In addition, rs2981582 in FGFR2, rs16886165 in MAP3K1 and rs3803662 in TOX3 are associated with breast cancer in populations of European ancestry, and the first two were also associated with breast cancer in Uruguay." (PMID 33126731, 2020). "FGFR2-ER-PR crosstalk leads to hormone-independent progression of breast cancer." (PMID 32971804, 2020). "FGFR2 mutations are also associated with increased risk of breast cancer in women without history of breast cancer in their family." (PMID 32676501, 2020). "As FGFR1 as well as FGFR2 are expressed in about 10% of breast cancers, these have gained attention for several purposes, including targeting newer treatments against these factors and using these as determinants of prognosis and overall survival of the patients." (PMID 31754359, 2019). "As a representative example, we consider the case of the FGFR2 gene in breast cancer." (PMID 30875371, 2019). "Prior studies have described associations of rs10510102 and rs2981579 (FGFR2) with breast cancer risk, but not specifically with Her2-positive breast cancers." (PMID 31125336, 2019). "A study carried out in a murine model of MPA (medroxyprogesterone acetate - synthetic progestin)-induced mammary carcinoma has revealed that hormone-independent (HI) tumours were characterised by a higher level of FGFR2 expression than their hormone-dependent counterparts." (PMID 31142340, 2019). "In addition, we illustrate how breast cancer pathway analysis can be confounded by the frequency of FGFR2 in pathway lists." (PMID 30875371, 2019). "FGFR2 activation has been shown to repress the activity of the estrogen receptor (ER) regulon, which has been correlated with poor prognosis in a cohort of ER+ breast cancer patients." (PMID 30405704, 2018). "In addition, FGF stimulation of the FGFR2-overexpressing breast cancer cell line SUM-52PE also enhanced STAT3 tyrosine phosphorylation and transcriptional activity, which was strongly reduced by FGFR2 knockdown or pharmacologic inhibition." (PMID 29914167, 2018). "Association of FGFR2 and FGFR3 expression with ER+ breast cancer progression was observed." (PMID 29455658, 2018). "Furthermore, the knockdown of RUNX2 reduced the expression of FGFR2 in the breast cancer cell line MCT-758." (PMID 30202094, 2018). "rs60538652, on SIAH2, rs2912774 on FGFR2 and rs67129489 near PGAM1P5/NTN4 were more strongly associated with ER+ or PR+ cases, while rs9383936 near ESR1 was more strongly associated with ER− or PR− breast cancers (Pheterogeneity <0.05)." (PMID 30323354, 2018). "FGFR2 amplification is thought to occur in 5% of gastric cancers and 1%–4% of breast cancers." (PMID 28835367, 2017).
breast carcinoma (continued). "In a preclinical study conducted on human breast carcinomas from 58 patients, it was observed that the action of 17-β-estradiol altered the expression and/or localization of FGFR2 and that 62% of the tumor cells showed moderate to intense FGFR2 labeling in their cytoplasm." (PMID 28945747, 2017). "FGFR2 locus was one of the first breast cancer loci identified by GWAS." (PMID 27825120, 2016). "FGFR3 and FGFR4 amplification are less common than FGFR1 and FGFR2 in breast cancer." (PMID 27489863, 2016). "Yet our results suggest that FGFR2 plays a suppressive role in breast cancer." (PMID 27236187, 2016). "We have identified 36 TFs whose regulons are significantly enriched for genes associated with breast cancer risk loci (termed “risk TFs”), and four of these risk TFs (ESR1, FOXA1, GATA3 and SPDEF) have been identified as MRs of FGFR2-mediated risk in breast cancer." (PMID 27997592, 2016). "Interestingly, the excess of African ancestry in breast cancer cases extends over both FGFR2 and a second region spanning from 131 to 134 Mb on chromosome 10." (PMID 27708667, 2016). "Amplification of FGFR2 gene occurs in a small subset of breast cancer." (PMID 26911390, 2016). "Interestingly, FGFR2 addiction has been reported to be a mechanism leading to lapatinib resistance in breast cancer." (PMID 26022204, 2015). "For a second gene already associated with breast cancer, FGFR2 on chromosome 10q26.13, no SNP had p < 10−6 but 11 were associated at a less restrictive p < 10−5." (PMID 25956309, 2015). "But these observations need to be confirmed in further studies with larger sample size, to rule out false positive results and to establish intron 2 FGFR2 SNPs as breast cancer susceptibility loci." (PMID 25333473, 2014). "FGFR2 overexpression has been observed in breast cancer cell lines and breast tumor tissues." (PMID 25333473, 2014). "However, in certain breast cancer cell lines, silencing Fgfr2 with siRNA results in increased Fgfr1 levels, providing a precedent for our observations." (PMID 24824078, 2014). "Previously reported BRCA2-modifying alleles for breast cancer, including those in FGFR2, TOX3, MAP3K1, LSP1, 2q35, SLC4A7, 5p12, 1p11.2, ZNF365, and 19p13.1 (ER-negative only), are also associated with breast cancer risk in the general population and/or BRCA1 mutation carriers." (PMID 23544012, 2013). "SNP rs2981582 (10q26/FGFR2) was significantly associated with breast cancer risk in two studies, but not in the other studies." (PMID 23593120, 2013). "Mouse models of mammary carcinogenesis have long established the FGF signalling pathway as a major contributor to tumorigenesis, and a mouse mammary tumor virus (MMTV) insertional mutagenesis screen for genes involved in breast cancer has identified both FGFR2 and FGF10." (PMID 23527311, 2013). "We replicated previously reported breast cancer susceptibility alleles in these BRCA2 mutation carriers and for several regions (including FGFR2, MAP3K1, CDKN2A/B, and PTHLH) identified SNPs that have stronger evidence of association than those previously published." (PMID 23544012, 2013). "However, as yet, little is known about the mechanism by which FGFR2 and FGF10 mutations act as risk factors in predisposition to breast cancer." (PMID 23527311, 2013). "FGFR2 has been reported to act as an oncogene in breast cancer and increased FGF signalling might promote cancer initiation or progression by protecting the cells from apoptosis and stimulating growth and proliferation." (PMID 24265722, 2013). "The germline genetic profile of a patient can influence predisposition to specific cancer subtypes; in breast cancer, for example, FGFR2 variants are strongly associated with ER-positive but not ER-negative breast cancer." (PMID 24152305, 2013). "Since the data implicating the FGFR2 intron 2 haplotype in breast cancer are clear, from many independent studies, we hypothesise that there must be alternative SNPs impacting on cell behaviour." (PMID 24265722, 2013).